IDH1 (isocitrate dehydrogenase (NADP(+)) 1)
Diseases named in the same sentence as IDH1 in open-access papers (continued):
Sharing a sentence is not in itself a finding about the gene and the disease.
glioma (continued). "Data on clinical safety, tolerance, pharmacokinetics/pharmacodynamics (PK/PD), and antineoplastic activity of subjects with IDH1 R132H mutation in recurrent non-enhanced low-grade glioma will be studied." (PMID 31263678, 2019). "Some molecular genetic features including IDH1/2 mutation, MGMT promoter methylation, co-deletion of 1p/19q, TERT loss, and ATRX mutation have been reported to be associated with favorable prognosis in gliomas." (PMID 30658672, 2019). "In 2009, IDH1/IDH2 was found to be a good prognostic factor for low-grade gliomas." (PMID 32038995, 2019). "Our cohort was primarily composed of WHO grade II gliomas, with the exception of one WHO grade III IDHmut-noncodel glioma, and all tumors harbored an IDH1 R132 mutation." (PMID 31806013, 2019). "For example, the presence of IDH1 mutations and 1p/19q co-deletions are associated with better survival outcomes for grade II, III, and IV gliomas, which may be relevant for determining treatment options for lower grade glioma patients with worse prognoses." (PMID 31091655, 2019). "Identification of IDH1/2 (IDH) mutation and/or TERT promoter (pTERT) mutation is crucial for reaching a correct diagnosis and choosing the most appropriate treatment for patients harboring WHO grade II/III gliomas." (PMID 31889117, 2019). "For instance, PYCR1 could cooperate with isocitrate dehydrogenase 1 (IDH1) to promote cancer cell survival in glioma and esophageal squamous cell cancer." (PMID 31428683, 2019). "AGI-5198 treatment of mice engrafted with IDH1-mutant glioma removed repressive marks via significant reduction of H3K9 and H3K27 trimethylation at the promoters of genes associated with gliogenic (astrocytic and oligodendrocytic) differentiation, increasing the expression of these genes." (PMID 30857299, 2019). "We also aimed to determine the accuracy of tumor tissue for assessing the rs55705857 G allele and the relative risk of specific cancers in first and second-degree relatives of individuals with IDH1/2 mutated gliomas with and without the rs55705857 G allele." (PMID 30823903, 2019). "Targeting the impairments in metabolism and redox state might open up new avenues for treating IDH1-mutant gliomas." (PMID 31888244, 2019). "The IDH1 mutant is found in above 80% of grade II-III glioma tumors and secondary glioblastoma." (PMID 30708988, 2019). "In turn, this would suggest a reduced invasiveness of the IDH1R132H-expressing cells and may explain the better prognosis of patients with IDH1-mutant gliomas." (PMID 31242696, 2019). "A syngeneic glioma model of wild-type and IDH1-mutated cancers demonstrated no change in survival in RAG2 knockout mice, indicating that suppression of anti-tumor response mediates the competitive advantage of R-2-HG production in vivo." (PMID 31781488, 2019). "Indeed, IDH1 silencing in glioma cells that display co-activation of multiple RTKs (EGFR, the HGFR family member MSPR, and PDGFRs) enhances the efficacy of inhibitor combinations involving erlotinib, imatinib, and SU11274." (PMID 31010244, 2019). "A flow cytometry analysis of immune composition of human gliomas with a different IDH1 status demonstrated that human IDH1-mut gliomas have significantly lower infiltration of CD45+ immune cells, including microglia, macrophages, dendritic cells, B cells, and T cells, compared with IDH1-wt gliomas." (PMID 30857299, 2019). "IDH1 and IDH2 mutations in AML are mutually exclusive, as in glioma." (PMID 31165048, 2019). "In addition, The Tiantan Hospital and Yanda International Hospital in China also launched a clinical trial of “Safety and Effectiveness of IDH1 R132H-DC Vaccine in Glioma” (NCT02771301)." (PMID 31263678, 2019). "Robust, dose- and time-dependent 2HG depletion has been observed across a host of cell types including human chondrosarcoma cells and mouse-model xenografts, primary human AML myeloblasts, and mutIDH1R132H glioma xenografts (IC50 range 5–13 nM for various IDH1 mutants in vitro)." (PMID 31165048, 2019).
glioma (continued). "Patients with IDH1 mutations are thought to comprise secondary GBM as they are enriched for ATRX mutations similar to that found in lower-grade glioma and patients survive for a median survival of 31 months which is consistent with lower-grade glioma." (PMID 30778375, 2019). "Markedly reduced β-oxidation activity in IDH1 mutant gliomas may be involved in the reduction of energy production." (PMID 31278288, 2019). "The mean SDHC promoter methylation in the IDH1 mutant glioma samples was 2% (±SD 1.28, range 1–4%)." (PMID 31308404, 2019). "IDH-1 mutant transcripts have been found in EVs from glioma tumor cells suggesting that EVs could be involved in promoting neighboring glioma cells to increasingly utilize oxidative pathway for energy production." (PMID 32038644, 2019). "IDH1-mut gliomas showed reduced T-cell numbers and altered calcium signaling." (PMID 30857299, 2019). "However, we believe that the great potential of IDH1/2 inhibitors and vaccines will bring hope to glioma patients." (PMID 31263678, 2019). "It has been hypothesized that lower NADPH concentrations lead to decreased GSH levels and increased reactive oxygen species (ROS), and therefore more radiation induced DNA double-strand breaks in IDH1-mutant glioma cells." (PMID 31888244, 2019). "Furthermore, our data indicates that the myo-Inositol/tCho metabolite ratio is higher in mitochondrial IDH2 gliomas compared to cytosolic IDH1 gliomas." (PMID 30791611, 2019). "Additionally, AG-881 is in use in a phase 1 trial in IDH1/2-mutant gliomas and other solid tumors (ClinicalTrials.gov NCT02481154)." (PMID 31652645, 2019). "Firstly we undertook SDHC promoter methylation analysis on 17 IDH1 mutant glioma samples." (PMID 31308404, 2019). "Indeed, glioblastomas express IDH1 at higher levels compared to gliomas of lower grade (log2 expression levels of 10.9 ± 0.48 vs. 11.3 ± 0.49, vs. 11.4 ± 0.48 for grade II (n = 24), grade III (n = 85) and grade IV gliomas (n = 159) respectively)." (PMID 31240524, 2019). "In contrast, IDH1 overexpression renders glioma cells more resistant to this combo." (PMID 31010244, 2019). "To refine the diagnostic accuracy, we use Sanger sequencing, for example to detect rarer mutations in the IDH1, or IDH2 genes, histones, or to detect mutations in the TERT promoter either to support glioma diagnostics in the context of other mutations or to prognosticate meningioma recurrence risk." (PMID 30786920, 2019). "In glioma: clinical trials of IDH1/2 inhibitors, vaccines and new uses for old drugs." (PMID 31263678, 2019). "Nevertheless, many reports have shown that IDH1/2 mutant inhibitors could protect IDH1/2-muated glioma, chondrosarcoma, AML and colorectal carcinoma cells to multiple types of anti-cancer therapy, such as irradiation, daunorubicin, and PARP inhibitors." (PMID 31151327, 2019). "Moreover, large-scale genomic studies of central nervous system tumors have shown that patients with IDH1R132H have better clinical outcomes than those of patients with wild-type IDH1." (PMID 31151327, 2019). "Finally, they scan these loci of interest for genes whose expression is higher in IDH1 mutant gliomas, obtaining a final list of genes." (PMID 30405699, 2018). "To assess whether GNA13 might facilitate similar processes in ATRX-deficient human disease, we examined TCGA gene expression data for lower-grade glioma (LGG), focusing our analysis on those tumors harboring an IDH1 or IDH2 mutation." (PMID 29535300, 2018). "This variant is strongly associated with IDH1/2 mutant and 1p/19q codeleted glioma tumors, but data on these molecular markers was not available for the four GWAS datasets used." (PMID 29743610, 2018).
glioma (continued). "Interestingly, while 2HG levels promote the hypermethylator phenotype in gliomas, known as the CpG island hypermethylator phenotype (CIMP), IDH1 mutations are associated with better overall survival." (PMID 29342092, 2018). "The importance of glioma molecular profiling was underscored by the WHO in 2016, when it issued a new glioma classification based on certain mutations in the genes coding for isocitrate dehydrogenases (IDH1, IDH2) and 1p/19q codeletion." (PMID 31435515, 2018). "Consistently, previous studies showed that IDH1R132H transduction inhibited rather than stimulated tumor growth, and gliomas with IDH1 mutations possessed attenuated oncogenic signaling in comparison with those without." (PMID 30416682, 2018). "Mutations in isocitrate dehydrogenase 1 (IDH1), and less frequently in IDH2, occur in 80% of grade II and grade III astrocytomas and oligodendrogliomas, and are also found in high-grade glioblastomas that have arisen over time from these lower-grade gliomas." (PMID 29759978, 2018). "These negative associations arose between the IDH1 p.R132H driver mutation and signature 1, occurring in brain lower grade glioma and in glioblastoma multiforme." (PMID 30412573, 2018). "In our observations, we could not detect significant differences in lactate and acetate oxidation between wild-type and IDH1-mutant glioma cells." (PMID 30404651, 2018). "Opposite changes of 2HG and Glx levels in mutant IDH1 glioma (i.e., high 2HG and low Glx tumor levels) may make the 2HG/Glx ratio a metabolic biomarker that has an increased range to detect mutant IDH1 tumor tissue." (PMID 29662077, 2018). "IDH1 gene mutations in gliomas exhibit two unique features: the lack of loss of heterozygosity (LOH) and the lack of apparent inactivating mutations such as frameshift or truncations." (PMID 29439493, 2018). "These negative associations arose between signature 1 and IDH1 p.R132H in brain lower grade glioma and glioblastoma multiforme." (PMID 30412573, 2018). "MAF in LGG and IDH1/2 mutant glioma was similar among males and females." (PMID 29743610, 2018). "G-CIMP status is a characteristic feature of IDH1 mt gliomas." (PMID 29428975, 2018). "Based on the World Health Organization (WHO) Classification of Central Nervous System Tumours, both low grade and high grade gliomas can be divided into two categories according to the presence or absence of IDH1/2 mutations." (PMID 30574020, 2018). "Furthermore, we found that IDH1 mutant gliomas exhibit increased PYCR1 expression and that tumoral 2HG concentrations correlated with that of proline, suggesting that this effect is also observed in glioma patients." (PMID 29562167, 2018). "This study also allowed a more detailed classification of high-grade gliomas characterized by the absence of H3 and IDH1 mutations." (PMID 30279357, 2018). "However, to our knowledge, no quantitative locus-specific genome-wide characterization of 5hmC in IDH1 mt gliomas has been published." (PMID 29428975, 2018). "Other clinical-pathologic factors known to be associated with IDH1/2 WT gliomas, such as 1p/19q non-codeletion status, astrocytoma histology and older age, were also identified to significantly correlate with TAGLN2 expression in the TCGA analysis." (PMID 30647847, 2018). "Conflicting reports exist regarding the influence of IDH1 mutation on global levels of 5hmC in gliomas, and to date no quantitative genome-wide locus-specific interrogation of 5hmC status in IDH1 mutant (IDH1 mt) tumors has been published to our knowledge." (PMID 29428975, 2018).
glioma (continued). "Therefore, our data suggest that epigenetic silencing by promoter hypermethylation likely accounts for decreased TAGLN2 mRNA and protein levels observed in IDH1/2 mutant gliomas." (PMID 30647847, 2018). "The unique biology of 2HG makes this metabolite a very specific biomarker that can be used for the diagnostic, prognostic, prediction, and pharmacodynamics assessment by probing the tumor burden, cancer pathways, and treatment mechanisms in the mutant IDH1 gliomas." (PMID 29662077, 2018). "Since TAGLN2 was down-regulated in IDH1/2 mutant gliomas, we examined our global methylation data to determine whether increased promoter methylation may account for decreased TAGLN2 expression in these tumors." (PMID 30647847, 2018). "Applications of immune checkpoint inhibitors may be beneficial for chemoradiation-insensitive IDH1-wildtype gliomas." (PMID 29643764, 2018). "In fact, the introduction of the mutated IDH1 into human immortalized astrocytes induces extensive DNA hypermethylation and reshapes the methylome in a fashion that highly resembles the changes observed in G-CIMP+ lower-grade gliomas." (PMID 30279357, 2018). "By synergizing current knowledge of IDH1 activity in glioma with the emerging evidence of different enzyme kinetics between R132 IDH1 mutation subtypes, the translational potential in improving glioma management based on mutated IDH1 subtype in glioma is described." (PMID 29303363, 2018). "Additionally, single-cell RNA sequencing of IDH1-mt gliomas revealed the presence of a normal differentiation program in glioma CSCs across two lineages: astrocytes and oligodendrocytes." (PMID 30510501, 2018). "The cohort had several clinical and molecular characteristics: age ≥ 80 years (26.4%), lower-grade glioma (18.6%), preoperative KPS scores below 70 (51.4%), resection (34.3%), adjuvant RT + TMZ (68.6%), MGMT promoter methylation (48.6%), IDH1/2 mutation (7.7%) and TERT promoter mutation (60.9%)." (PMID 30076584, 2018). "Our results also suggest that TAGLN2 may be involved in progression due to higher expression in glioblastomas compared to IDH1/2 WT gliomas of lower grades." (PMID 30647847, 2018). "Somatic mutations of IDH1 and IDH2 have been reported to be associated with glioma CIMP." (PMID 29848370, 2018). "P8 was clinically judged as secondary GBM due to a previously diagnosed precursor lesion (low-grade glioma) and was therefore included in the analysis despite lack of IDH1 mutation." (PMID 29755294, 2018). "Moreover, we have shown that TAGLN2 is highly expressed in IDH1/2 WT gliomas and GBMs and appears to function as an oncogene." (PMID 30647847, 2018). "The underlying biological mechanisms accounting for improved clinical outcomes in IDH1/2 mutant gliomas remain poorly understood, but may, in part, be due to the glioma CpG island methylator phenotype (G-CIMP) and epigenetic silencing of genes." (PMID 30647847, 2018). "We investigated 350 glioma patients for the expression of the key EMT factors SLUG and TWIST by immunohistochemistry and immunofluorescence related to morpho-genetic alterations such as EGFR-amplification, IDH-1 (R132H) mutation and 1p/19q LOH." (PMID 29844871, 2018). "Recently, some cases of gliomas have been found to be associated with somatic mutations in the gene encoding isocitrate dehydrogenases (IDH) 1/2, with point mutations at highly conserved residues in the active sites of IDH1 (e.g. R132H) and IDH2 (e.g. R172K)." (PMID 30192797, 2018). "Notably, IDH1/2 was wild-type in 4 of 7 grade II gliomas (57.1%) and 13 of 18 grade III (72.2%) (Online Resource 3)." (PMID 30076584, 2018). "In addition, IDH1 mutation occurs predominantly in the proneural GBM subtype and is associated with the Glioma CpG Island Methylator Phenotype (G-CIMP)." (PMID 29428975, 2018).
glioma (continued). "Mutations in IDH1 or IDH2 genes, which encode isocitrate dehydrogenase enzyme involved in tricarboxylic acid cycle (TCA), are common in lower grade and anaplastic (II–III) glioma." (PMID 30327965, 2018). "Thus, diffuse gliomas (WHO grades II–IV) are now molecularly stratified based on IDH1 or IDH2 mutational status, with gliomas of WHO grade II and III being stratified according to 1p/19q codeletion status." (PMID 30279357, 2018). "Although similar to the Cho/NAA ratio (i.e., high Cho and low NAA tumor levels) in wild-type gliomas, the 2HG/Glx ratio may be more specific to detect the targeted treatment response against mutant IDH1 gliomas." (PMID 29662077, 2018). "To validate the expression pattern of WBP2 in wild-type glioma, we excluded the 20 specimens with IDH1/2 mutation and found that WBP2 was highly expressed in 78.2% of wild-type glioma samples (43/55), in which 36 samples defined as grade III glioma presented high WBP2 expression." (PMID 29497031, 2018). "Subsequently, we tested the hypothesis that increased TAGLN2 expression may contribute to worse prognoses in IDH1/2 WT gliomas by investigating the role and regulation of TAGLN2 regulation in both LGGs and GBMs." (PMID 30647847, 2018). "In gliomas, the use of hypomethylating agents reduced DNA methylation of promoters involved in glial cell differentiation and reduced cell proliferation in human derived IDH1 mutant glioma xenografts." (PMID 29342092, 2018). "To determine whether IDH2 mutant cell lines would also demonstrate a similar response, we created two cell lines using the WT IDH LN18 glioma as parental, to either express IDH1 R132H or IDH2 R172K." (PMID 29562167, 2018). "Although the relationship between IDH1/2 mutational status and sensitivity to CHQ in gliomas remains to be established, the recently proposed hypothesis that IDH1/2 mutations might be predictive of the efficacy of CHQ in gliomas seems plausible." (PMID 30211116, 2018). "In summary, we demonstrate that 2HG imaging can inform the phase I clinical trial on the biological effects of targeted therapies against mutant IDH1 gliomas, and potentially it could be used to guide future trial designs." (PMID 29662077, 2018). "The clinical evidence for the efficacy of radiation in IDH1 mutant gliomas is mixed." (PMID 29692895, 2018). "The scope of this analysis was to uncover the mechanisms that explain the action of the mutant IDH1 inhibitors in glioma patients, and determine a comprehensive panel of imaging biomarkers that can be used to objectively assess the response to mutant IDH1 inhibition." (PMID 29662077, 2018). "It has been shown in in silico studies that IDH1-mutant gliomas have significantly higher lactate dehydrogenase B expression comparing to wild-type tumours; and higher lactate oxidation was hypothesised in IDH1 mutation bearing cells." (PMID 30404651, 2018). "Furthermore, our results suggest that TAGLN2 functions as an oncogene by contributing to proliferation and invasion when overexpressed in IDH1/2 WT glioma cells." (PMID 30647847, 2018). "Some molecular genetic features including IDH1/2 mutation, MGMT promotor methylation, codeletion of 1p/19q, TERT loss, and ATRX mutation have been reported to be associated with favorable prognosis in gliomas." (PMID 29110682, 2017). "In addition, IDH1 mutant glioma cells show greater flux through pyruvate carboxylase leading to greater production of oxaloacetate." (PMID 28491867, 2017). "It has been recently demonstrated that IDH1 mutant gliomas respond to NAMPT inhibition." (PMID 29245920, 2017).